DNMT3A (DNA methyltransferase 3 alpha)
Diseases named in the same sentence as DNMT3A in open-access papers (continued):
Sharing a sentence is not in itself a finding about the gene and the disease.
acute myeloid leukemia (continued). "Somatic mutations in genes such as NPM1, which is involved in the maintenance of HSCs’ quiescence and self-renewal, and TET2, DNMT3A, involved in mediating HSCs’ differentiation, results in the transformation of HSCs thereby leading to the development of Acute Myeloid Leukemia (AML)." (PMID 38571491, 2024). "A case study documented the detection of high-risk CH variants DNMT3A exon 23 p.R882H and isocitrate dehydrogenase 2 (IDH2) exon 4 p.R140Q at a low VAF in a patient with prostate cancer who developed acute myeloid leukemia a year later, driven by the same mutations." (PMID 40027147, 2024). "However, one study showed that patients with acute myeloid leukemia with the CG/GG genotype tended to express DNMT3A mRNA 2.38 times higher compared to individuals with the CC genotype." (PMID 37372315, 2023). "In Professor Qian’s talk—“Development of a novel therapeutic approach against DNMT3A-mutant acute myeloid leukemia”—he reminded the audience how DNMT3A was the most frequently mutated gene in ARCH, and was associated with increased risk of hematologic malignancies including AML." (PMID 38023340, 2023). "The methyltransferase domain of DNA methyltransferase protein 1 is an essential functional domain in acute myeloid leukemia, which is independent of DNMT3A mutation." (PMID 36329185, 2022). "DNMT3A and IDH1/2 mutations combinatorically regulate the transcriptome and the epigenome in acute myeloid leukemia; yet the mechanisms of this interplay are unknown." (PMID 36316347, 2022). "G4-based MTase inhibitors may be beneficial in treating various cancers, such as acute myeloid leukemia, characterized by genome hypermethylation and the presence of mutant Dnmt3a proteins." (PMID 36142137, 2022). "While mutations in DNMT3A act as negative prognostic factor in patients with acute myeloid leukemia (AML), DNTM1 ablation in Teffs and its inhibition by DNMTs inhibitor 5-aza-2′-deoxycytidine (Aza) lead to an increase in Foxp3 expression in these cells." (PMID 34281195, 2021). "Overexpression or enhanced catalytic activity of DNMT1, DNMT3a, and DNMT3b has been observed in multiple cancers, including acute myeloid leukemia (AML), chronic myeloid leukemia (CML), glioma, and breast, gastric, colorectal, hepatocellular, pancreatic, prostate, and lung cancers." (PMID 33572577, 2021). "Non-congenital or somatic variants in DNMT3A can be found in patients with acute myeloid leukemia (AML), myelodysplastic syndrome, and myeloproliferative syndromes." (PMID 33194904, 2020). "The specific relevance of DNMT3A mutations to the cancer phenotype has not been explored, except for p.R882 mutations, which predict poor prognosis in acute myeloid leukemia." (PMID 28505169, 2017). "In this light, the frequent co-occurrence of DNMT3A and NPM1 mutations suggests that the former behave as “rafts” that enable NPM1 mutant clones to be founded and expanded, thus facilitating onward evolution toward acute myeloid leukemia." (PMID 25732814, 2015). "For instance, genes encoding epigenetic modifying enzymes, including DNA (cytosine-5)-methyltransferase 3A (DNMT3A) and isocitrate dehydrogenase IDH1/2, were mutated at a high frequency in the founding clones of human acute myeloid leukemia (AML)." (PMID 37894295, 2023). "hsa-miR-6718 may be related to DNMT3A-mutant acute myeloid leukemia patients." (PMID 35279104, 2022). "In analogy to prostate cancer, truncal point mutations in DNMT3A and gene fusions in PML-RARA are mutually exclusive drivers in acute myeloid leukemia (AML)." (PMID 33531470, 2021). "In this study, we aimed to investigate the impact of DNMT3A status on NPM1 MRD predictive value for survival in a retrospective cohort of acute myeloid leukemia (AML) patients aged over 60 years old treated intensively." (PMID 33947035, 2021).
acute myeloid leukemia (continued). "Notably, an aberrant function of the DNA methyltransferase DNMT3A, caused by a recurrent, somatic R882H mutation in hematopoietic stem cells was identified as a key event in the emergence of pre-leukemic hematopoietic stem cells, and the subsequent onset of acute myeloid leukemia (AML)." (PMID 34775469, 2021). ", which was used to analyze the DNMT3A/B mRNA levels of acute myeloid leukemia (AML) cells following miR-29 upregulation." (PMID 30469344, 2018). "In acute myeloid leukemia (AML), mutations in DNA methylation regulators such as DNMT3A, TET2, IDH1 and IDH2 are frequent, and loss of function of TET2 and DNMT3A are early events in leukemogenesis." (PMID 26829670, 2016). "Mutations in the human DNA methyl transferase 3A (DNMT3A) gene are recurrently identified in several hematologic malignancies such as Philadelphia chromosome-negative myeloproliferative neoplasms (MPN), myelodysplastic syndromes (MDS), MPN/MDS overlap syndromes and acute myeloid leukemia (AML)." (PMID 24914952, 2014). "Mutations in the genetic sequence of the DNA de novo methyltransferase DNMT3A (DNA methyltransferase 3A) are found in many patients with acute myeloid leukemia (AML)." (PMID 24280869, 2014). "Acute myeloid leukemia (AML) with a normal karyotype (CN-AML), which accounts for 40–50% of AML cases, commonly presents with genetic mutations in ASXL1, MLL, DNMT3A, TET2, IDH1 and IDH2 genes, all of which have important roles in epigenetic regulation." (PMID 24202321, 2013). "In the last 3 years, alone mutations in the genes TET2, IDH1, IDH2, DNMT3a, and EZH2 have all been found in patients with myeloproliferative neoplasms (MPNs), myelodysplastic syndromes (MDSs), and/or acute myeloid leukemia (AML)." (PMID 21811504, 2012). "MiR-101 acts as tumor suppressor in lung and breast cancer, by negatively regulating DNMT3A and EZH2; miR-193 targets DNMT3A and HDAC in acute myeloid leukemia cells." (PMID 41595461, 2025). "For instance, mutations in DNMT3A and TET2 disrupt normal clonal hematopoiesis and are implicated in the transformation of HSCs into myelodysplastic syndromes (MDS) and acute myeloid leukemia (AML) 10-12." (PMID 40657362, 2025). "DNMT3A had elevated levels in CHOL, acute myeloid leukemia (LAML), skin cutaneous melanoma (SKCM), TGCT, THYM, and uveal melanoma (UCS)." (PMID 38666956, 2024). "The first identified example of epi-miRNAs was the miR-29 family members (29a, 29b, and 29c); they regulate the expression of DNMT3A and DNMT3B in lung cancer and acute myeloid leukemia (AML)." (PMID 34281210, 2021). "For example, findings from acute myeloid leukemia cells have indicated strong impact of miR-29 family members on three target DNMT izoenzymes: DNMT1, DNMT3A and DNMT3B resulting in global DNA hypomethylation as well as reexpression of tumor suppressor genes." (PMID 33803981, 2021). "Acute myeloid leukemia (AML) is a heterogeneous malignancy with the most common genomic alterations in NPM1, DNMT3A, and FLT3." (PMID 32754299, 2020). "And interestingly, miR-29 family reverted global gene methylation by targeting DNMT3a and DNMT3b directly in non-small-cell lung cancer (NSCLC) and acute myeloid leukemia cells." (PMID 29849932, 2018). "A previous study has also reported that miR-29b promotes global DNA hypermethylation by targeting directly DNMT3A and 3B and indirectly DNMT1 in acute myeloid leukemia." (PMID 28886082, 2017). "However, DNA methylation profiling of DNMT3A-mutant acute myeloid leukemia (AML) patient samples showed regional increases as well as decreases in methylation, and changes in gene expression were poorly correlated to changes in DNA methylation." (PMID 28923089, 2017). "Included were DNMT3A R882 and NPM1 W288, which occur in 14.9 and 25.6 % of acute myeloid leukemia (LAML) patients, respectively and have been shown important in LAML oncogenesis." (PMID 27356755, 2016).
acute myeloid leukemia (continued). "DNMT3A, FLT3, and NPM1 mutations are among the most common genomic alterations in de novo acute myeloid leukemia (AML) and play a key role in the pathogenesis and evolution of the disease, particularly in the absence of AML-associated recurrent cytogenetic abnormalities." (PMID 25281355, 2014). "This point was already addressed by others who demonstrated that downregulation of DNMT3A and DNMT3B led to regulation of ESR1 or ESR2 via promoter DNA aberrant methylation in acute myeloid leukemia, endometriosis, prostate and ovarian cancer." (PMID 23626723, 2013). "In acute myeloid leukemia, TDG interacts with DNMT3A to reduce its methylation ability." (PMID 35414793, 2022). "Following studies provided further evidence regarding the incidental and non-malignant significance of the persistence of DNMT3A, TET2 and ASXL1 mutations detectable by NGS after initial induction chemotherapy for acute myeloid leukemia (AML)." (PMID 33562056, 2021). "DNMT1, DNMT3A, and DNMT3B are overexpressed across several types of cancer lineages, including acute myeloid leukemia (AML), melanoma, breast cancer, colorectal cancer, prostate cancer, and stomach cancer." (PMID 36329185, 2022). "KO-539 induces complete remission (CR) in two out of six patients with relapsed/refractory acute myeloid leukemia (R/R AML), including a minimal residual disease (MRD)-negative CR in a NPM1-mutated AML patient co-mutated for DNMT3A and KMT2D." (PMID 38255885, 2024).
leukemia (188 papers, 2009 to 2026). A malignant (clonal) hematologic disorder, involving hematopoietic stem cells and characterized by the presence of primitive or atypical myeloid or lymphoid cells in the bone marrow and the blood. "In summary, results from multiple AML models demonstrate that the proposed combo treatment exhibits significant in vivo activity, evidenced by reduced leukaemia growth and prolonged survival in DNMT3A-mutated xenograft models." (PMID 40240608, 2025). "Large TBRS series and syntheses do not identify anemia as a consistent phenotypic element, although the role of DNMT3A in hematopoiesis and the reported leukemia risk justify routine hematologic surveillance." (PMID 41384217, 2025). "CHIP arises in older individuals due to leukaemia-associated mutations, primarily in epigenetic modifiers DNMT3A, TET2 and ASXL1, within haematopoietic stem cells (HSCs), leading to the emergence of pre-leukaemic cells." (PMID 40269158, 2025). "Mutation of DNMT3a can affect the DNA methylation levels of leukaemia-related genes, thus exerting carcinogenic effects by blocking haematopoietic cell differentiation and promoting excessive proliferation." (PMID 39990668, 2025). "Mutation of DNMT3A has been identified in ~15–20% of leukemia patients, with the R882 mutations (in an occurrence order of R882H > R882C > R882P, R882S) accounting for over 50% of all missense mutations." (PMID 38600075, 2024). "In leukemia, mutations of DNMT3A, especially in R882H, are one of the most frequent recurrent genetic changes in AML." (PMID 36797244, 2023). "Patients with DNMT3A mutation had a higher risk for progression to leukemia, with an overall hazard ratio of 6.87 (p < 0.05, 95% CI = 2.80–16.87)." (PMID 36982819, 2023). "A recent study showed that the combined mutation of NPM1/TET2/FLT3-ITD and DNMT3A observed in about 4% of NPM1-mut AMLs resulted in an aggressive leukemia phenotype." (PMID 37509445, 2023). "Our studies show that PI3K pathway plays a crucial role in Dnmt3a loss–driven myeloid malignancy in multiple places during the progression to leukemia." (PMID 36976647, 2023). "Recently, it was suggested that SF3B1, SRSF2, ASXL1, TET2, and DNMT3A gene mutations contribute to the risk of MDS evolution to leukemia and also influence therapy response and overall survival." (PMID 36982819, 2023). "DNMT3A mutations are an early preleukemic event, which — when combined with other genetic lesions — result in full-blown leukemia." (PMID 36976647, 2023). "The relationship between the type of DNMT3A mutation and clinical outcomes remained controversial in leukemia patients." (PMID 36797244, 2023). "Similar studies have also demonstrated that Dnmt3a deletion or mutations cooperate with Flt3ITD, Npm1c, or cKIT in leukemia transformation." (PMID 38028538, 2023). "Mutations in the DNMT3A gene are less frequently observed in MM compared to the other types of leukemia." (PMID 36059621, 2022). "MDS patients with DNMT3A mutations had a higher risk of leukemia transformation and shorter overall survival." (PMID 35296003, 2022). "DNMT3A is one of the most frequently mutated genes in clonal hematopoiesis and leukemia, indicating that it plays a crucial role for hematopoietic differentiation." (PMID 35705990, 2022). "This imbalance between self-renewal and differentiation is believed to underlie the propensity of DNMT3A mutations to contribute to clonal hematopoiesis and leukemia." (PMID 35635747, 2022).
leukemia (continued). "NPM1 mutations correlate with most mature stages of leukemia arrest together with TET2 or IDH mutations in granulocyte progenitors-like AML or with DNMT3A mutations in monocyte progenitors-like AML." (PMID 35973983, 2022). "Overall, oridonin is a potential and promising drug candidate or lead compound targeting DNMT3A R882 mutation-driven clonal hematopoiesis and leukemia." (PMID 34663800, 2021). "To better understand the cellular effects of Bcor and Dnmt3a loss in vivo, we analysed PB and BM samples of unmutated, single and double knockout mice at both early and overt leukemia stages." (PMID 33159179, 2021). "DNMT3A mutation in mice promotes the development of leukemia by upregulating CDK1 through the mTOR pathway." (PMID 34093541, 2021). "In spite of the antagonism between IDH and DNMT3A mutations concerning the DNA methylation effects, these two epigenetic mutations were recently shown to cooperate to induce leukemia." (PMID 32859092, 2020). "By Kaplan-Meier analysis, only DNMT3A overexpression was associated with longer overall survival (OS) and leukemia-free survival (LFS) in whole-cohort AML (P=0.001 and 0.003, respectively)." (PMID 32597790, 2020). "To understand the mechanism underlying the biological effect of DNMT3A mutants in KMT2A-PTD-positive leukemia, we examined the patient samples harboring both KMT2A-PTD and DNMT3A-WT/MT by using global gene expression microarray analysis." (PMID 32015320, 2020). "Kaplan-Meier analysis showed that DNMT3A expression was associated with better overall survival (OS) and leukemia-free survival (LFS) among whole-cohort AML, and independently affected OS determined by Cox repression multivariate analysis." (PMID 32597790, 2020). "By bioinformatics analysis, DNMT3A expression was found to be positively correlated with several leukemia-associated genes/microRNAs, and DNMT3A was identified as direct targets of miR-429 and miR-29b in AML." (PMID 32597790, 2020). "Our study thus provides a unique mouse model that recapitulates many aspects of human AML and a potential therapeutic target for DNMT3A mutation-related leukemia." (PMID 31703632, 2019). "As one of common epigenetic alterations in AML, DNMT3A mutation has been demonstrated to play an important role in the pathogenesis of leukemia." (PMID 31703632, 2019). "The patient (UPN 37) who had least increase in variant allele frequency of DNMT3A mutation during disease progression acquired RUNX1 mutation at leukemia transformation." (PMID 29619119, 2018). "Their variant allele frequencies of DNMT3A and other co-occurring mutations were increased at least 10% (10.0–347.1%) at leukemia transformation compared with those at baseline." (PMID 29619119, 2018). "The mutations in HSCs that initiate sporadic leukemia in adults generally occur in genes encoding epigenetic regulatory proteins such as DNMT3A, ASXL1, IDH2, and TET2." (PMID 29326930, 2017). "And in leukemias, loss of DNMT3A activity is associated with hypomethylation around CpG islands and deregulation of Hox genes." (PMID 29074627, 2017). "In vivo experiments suggest that the mutation or deletion of Dnmt3a induces the development of leukemia by cooperating with oncogenic factors, such as RAS mutation, c-Kit variation, or FLT3-ITD abnormalities." (PMID 28127428, 2017). "As observed with AML, MDS patients with R882 mutations are seen to have a significantly worse overall prognosis and a more rapid progression to leukaemia than those patients with non-R882 DNMT3A mutations." (PMID 28286768, 2017). "Does the presence of a DNMT3A mutation, which in a normal individual only modestly increases the risk of leukemia, confer a much greater risk in the context of an inherited RUNX1 mutation?" (PMID 29326930, 2017). "The mechanism by which mutations in DNMT3A trigger the development of leukemia are still unclear; however, it has been observed that mutations DNMT3A act dominantly negatively on the activity of wild DNMT3A." (PMID 29340131, 2017).